ZFP36 (ZFP36 zinc finger CCCH-type)
Diseases named in the same sentence as ZFP36 in open-access papers (continued):
Sharing a sentence is not in itself a finding about the gene and the disease.
ZFP36 also shares sentences with these, for which no sentence is quoted: acute myeloid leukemia (2 papers); Liver Cirrhosis (2); squamous cell carcinoma (2); acute lung injury (1); allergic disease (1); anemia (1); autoimmune encephalitis (1); B cell lymphomas (1); bacterial vaginosis (1); breast (1); Cachexia (1); Cardiomyopathies (1); Cirrhosis (1); colorectal neoplasm (1); fibrosis (1); heart failure (1); hematological malignancies (1); hypertrophy (1); idiopathic cardiomyopathy (1); immune disorder (1); inflammation (1); Intellectual disability (1); ischemic cardiomyopathy (1); juvenile idiopathic arthritis (1); Kaposi's sarcoma (1); lymph node metastasis (1); malignant glioma (1); Marfan syndrome (1); multiple sclerosis (1); myocardial ischemia (1).
A further 18 diseases each share a sentence with ZFP36 in 1 paper.